HRAS (HRas proto-oncogene, GTPase)
Diseases named in the same sentence as HRAS in open-access papers (continued):
Sharing a sentence is not in itself a finding about the gene and the disease.
cancer (continued). "KRAS-4B has been shown to be most expressed across a range of cancer cell lines and healthy mouse tissue, followed by KRAS-4A, NRAS and lastly HRAS." (PMID 39372214, 2024). "Our study identifies BAY 11-7082 to be an efficacious inhibitor for treating RAS oncogene (HRAS, KRAS, and NRAS) mutant cancer cells." (PMID 38982514, 2024). "We treated multiple NRAS (SKMEL-103, M245, and SKMEL-2), KRAS (AsPC1, PANC1, and SU.86.86), and HRAS (RH-36 and SMS-CTR) mutant cancer cell lines with different concentrations of BAY 11-7082 and measured cell viability." (PMID 38982514, 2024). "Next, we continued our selectivity assessmentby testing the antiproliferative activity of the top three compoundsfrom each round on KRAS, HRAS, or BRAF mutant cancer cells." (PMID 38758695, 2024). "A PPI network analysis was used to identify 17 potential targets of saponins aglycone in cancer cells, and the binding modes of saponins aglycone to four of these targets (BRD3, GLO1, CDK6, and HRAS) were confirmed using docking and MD simulations." (PMID 37996449, 2023). "Among 33 cancer types analyzed by Pan TCGA, the TP63 and HRAS genes are significantly overexpressed in human head and neck and lung SCCs compared to normal tissues." (PMID 37638000, 2023). "Of note, circ_63706 knockdown downregulated genes contributing to important cancer pathways including RBBP4, TGFA, E2F1, and HRAS." (PMID 36899402, 2023). "Among the three isoforms (KRAS, NRAS, and HRAS), Kirsten rat sarcoma viral oncogene homolog (KRAS) is the common oncogene in a large percentage of cancers, including pancreatic cancer, non-small cell lung cancer (NSCLC), and colorectal cancer." (PMID 37662925, 2023). "The expression of these paralogues differs between cell types and cancer types; thus, it is likely that the combined stoichiometry of KRAS, HRAS, and NRAS proteins drives the cellular and in vivo phenotypes." (PMID 36980522, 2023). "Using several cellular models of mutant HRAS and NRAS-driven cancers, this study evaluated the interaction of AGO2 with these RAS isoforms and elucidated the functional implications of this interaction." (PMID 35923912, 2022). "These cell lines showed a spectrum of genetic dependencies on KRAS, HRAS, BRAF, CALM1-3 (the three human CaM genes), the alpha isoform of the C subunit of the PP2A enzyme (PPP2CA) and an endogenous inhibitor of PP2A in cancer, SET." (PMID 35617282, 2022). "Taken together, our study finds a novel role for AGO2 as a regulator of cellular proliferation and senescence in mutant HRAS and NRAS-driven cancers through an EGFR–AGO2–RAS signaling axis." (PMID 35923912, 2022). "AMG510 demonstrated exquisite engagement selectivity for KRAS(G12C) compared with KRAS WT, other KRAS hotspot mutants, and HRAS WT, consistent with previous reports for functional selectivity between KRAS(G12C) and non-G12C driven cancer cell lines." (PMID 35314814, 2022). "The novel therapeutic development targeting KRAS-mutant cancers also works on discovery of pan-Kras inhibitors and proteolysis targeting chimeras (PROTAC) which avoid HRAS and NRAS." (PMID 36359850, 2022). "In parallel to our studies with mutant KRAS, we set out to identify a role for AGO2 in mutant HRAS and NRAS-driven cancers." (PMID 35923912, 2022). "The prognostic signature that we constructed consisted of seven cancer driver genes (CDKN2C, HRAS, IRAK1, LOX, MYCN, NRAS, and PABPC1)." (PMID 36017503, 2022). "HRAS, a member of the RAS gene family that is closely related to multiple human cancers, and studies have shown that it engages in mediating EMT of HCC cells through the TGF-β1/HRAS axis, thereby promoting tumor invasion and metastasis." (PMID 36463115, 2022). "Many of these genes were transcription factors and several of them were known cancer genes (e.g., APC, BCL2, ERBB2, HRAS, TGFBR2)." (PMID 35008420, 2022).
cancer (continued). "After assessing the endogenous regulators of the AGO2–RAS interaction, we next asked if AGO2 played a functional role in promoting mutant HRAS and NRAS cancers." (PMID 35923912, 2022). "While nearly 85% of RAS-driven cancers are KRAS mutants, HRAS and NRAS share approximately 82% to 90% of the amino acid (aa) sequence with KRAS, with the majority of variance occurring within the C-terminal region." (PMID 35923912, 2022). "Surprisingly, BCL2L1, E2F1, HRAS, MAPK8, MITF, RELA, and SP1 were all found in the mitophagy and cancer pathways." (PMID 34262589, 2021). "RAS mutations are the most commonly found oncogenic alteration in human cancers, most frequently observed in KRAS (85%), and to a lesser degree in NRAS (12%) and HRAS (3%)." (PMID 34919052, 2021). "Those events occurred on pre-mRNA of 56 genes including well-known cancer-related genes PTPRC, IKBKB and HRAS, and genes coding for transcription factors ILF2, ATF2 and EYA3." (PMID 34543356, 2021). "Mutations on the G12/G13 positions in Ras proteins, including HRAS, KRAS, and NRAS, showed increased sensitivity to MEK inhibitors AZD6244 and PD-0325901 in multiple cancer types (BLCA, CESC, HNSC, PAAD, THYM, UCEC, and UCS)." (PMID 33741950, 2021). "A recent study has demonstrated that oncogenes found in many cancer entities, such as MYC, aurora kinase B (AURKB) and HRAS, trigger hyperactivation of ESCRT and ceramide pathways, as well as the inhibition of lysosome genes causing abundant sEV secretion." (PMID 34503190, 2021). "HRAS degradation by the proteasome was blocked by the WNT/β-catenin pathway linking WNT signaling and sustained RAS activation in cancer." (PMID 34062774, 2021). "The following figure shows the Alteration frequency type of EGFR, HRAS and MAPK3 in four types of cancer." (PMID 34764329, 2021). "KRAS, NRAS proto-oncogene GTPase (NRAS), and HRas proto-oncogene GTPase (HRAS) are members of RAS proto-oncogenes family (RAS) and they play an important role in human cancers." (PMID 35048058, 2021). "The RAS family of proteins (KRAS, HRAS, and NRAS) are well-known oncogenic drivers in various cancers." (PMID 32760207, 2020). "Thousands of direct gene targets of this drug are verified (these genes are significantly enriched in cancer such as SRC and HRAS)." (PMID 32328408, 2020). "In the network diagram of the pathway, HRAS-related pathways, such as “RAS Signaling”, “PI3K/AKT Signaling in Cancer”, “Autophagy”, “ERK/MAPK targets”, and “Mitophagy”, were predicted to be involved." (PMID 33036162, 2020). "BILD_HRAS_ONCOGENIC_SIGNATURE pathway can discriminate cells expressing activated HRAS from control cells expressing GFP and distinguish between specific cancers and tumor subtypes." (PMID 32714860, 2020). "The proximal interactions of these SNAREs were assessed by a similar experimental design for KRAS, HRAS, and NRAS in cells derived from the most cancer-relevant tissues for each isoform." (PMID 31712554, 2019). "Collectively, these results indicate that HRAS G12V mainly activates the canonical downstream pathways of RAS, triggering changes in gene expression that facilitate cancer cells proliferation and survival." (PMID 31681616, 2019). "A genomic study performed in a large cohort of PTC from Saudi Arabia (n = 886), where thyroid cancer is the second most common cancer in women, showed a high prevalence of BRAF (59%), HRAS (2%), and NRAS (1%), similar to other cohorts." (PMID 31835496, 2019). "Our analyses resulted in the identification of an ER-positive HRAS-/PIK3CA-/AKT1-wild type AME harboring an HMGA2-WIF1 fusion gene, which has been described in PAs and carcinomas ex-PA of the salivary gland." (PMID 30675516, 2019).
cancer (continued). "On the other hand, higher expression of HRAS, NRAS, APC, HFE, MMP9, and a high enrichment of MAPK/RAS, NFKB, and TNF signaling pathways are all evident in HLE cells as often seen in cancer." (PMID 30176945, 2018). "It is known that in cancer cells, NRAS and KRAS are often hyperactivated in comparison with HRAS and therefore NRAS and KRAS are much more important therapeutic targets in cancer when compared to HRAS14,15." (PMID 29891945, 2018). "We modify the HaCaT keratinocyte cell line model to simulate cancer cells with constitutive activation of EGFR, HRAS, and PI3K in a controlled genetic background." (PMID 27650546, 2016). "Finally, we show that this previously unknown weakness of the HRAS gene points to a new mechanism for knocking out oncogenic HRAS by employing SSOs that block binding of the required splicing regulatory factors, resulting in exon 2 skipping and decreased growth of cancer cells." (PMID 27195699, 2016). "With the exception of the relatively well-known KRAS, HRAS and NRAS proteins, little is known about how the interactions of the other RAS human paralogs affect cancer evolution and response to treatment." (PMID 27713118, 2016). "Starting from the cancer genes KRAS, NRAS and HRAS (that we will name RAS trio), similar in structure and mutational profile, we seek to extend this conservation to all the Ras superfamily members (in total, 133 different proteins belonging to the PF00071)." (PMID 26860319, 2016). "Thus, our data may encourage clinical studies on HRAS mutant cancer patients." (PMID 26544513, 2015). "In cultured cells, wild-type HRAS, NRAS or KRAS have been shown to promote proliferation of oncogenic RAS-driven cancer cell lines by mediating EGF signaling." (PMID 25902334, 2015). "It is worth noting that five of these genes (PIK3CA, HRAS, AKT1, ETV6, and KDM5C) are known to play important roles in cancer and are CGC genes (that is, experimentally validated cancer genes)." (PMID 25360158, 2014). "KRAS, NRAS, HRAS, BRAF, PIK3CA, PIK3R1 and PTEN are key cancer-related genes in the RAS/RAF and PI3K/PTEN signaling pathways." (PMID 25120700, 2014). "Among them, the following well-known cancer genes were found: MET, CDK4, MDM4, EGFR and PIK3CA (amplifications), and CDKN2A, MLLT3, HRAS, CARS and NF1 (deletions)." (PMID 23408991, 2013). "Mutations in KRAS occur with the greatest frequency in all human cancers (21.6%), followed by NRAS (8.0%), and HRAS (3.3%)." (PMID 23202889, 2012). "We recently identified somatic activating mutations in genes associated with the AKT and MAPK signaling pathways, including PIK3CA, KRAS, HRAS, and NRAS, in BM from breast and other cancers." (PMID 22567347, 2011). "Accordingly, BAY 11-7082 could be considered an effective inhibitor targeting NRAS, KRAS, and HRAS mutant cancer and serve as a promising candidate for more effective treatments tailored to all RAS-mutant cancers." (PMID 38982514, 2024). "Among central nodes were ERBB2 (v-erb-b2 avian erythroblastic leukemia viral oncogene homolog 2), CRK (Cysteine-rich receptor-like-kinase), HRAS, and KRAS (Kirsten rat sarcoma virus), all of which were proto-oncogenes involved in the development of various cancer types." (PMID 38304545, 2024). "Dysregulation of HRAS and STAT3 pathways is frequently observed in several cancers." (PMID 37298367, 2023). "In our models of RMS, tipifarnib selectively inhibited tumor growth in HRAS-mutant xenografts early in the treatment course and without toxicity, consistent with other mouse models of HRAS-mutant cancers." (PMID 35459782, 2022).
cancer (continued). "Remarkably, while enhanced MAPK1 activation associated with oncogenic mutations in upstream signal transducers (e.g., KRAS, HRAS, NRAS, and BRAF) is a common finding in cancer, MAPK1 mutations do not represent a major somatic event contributing to oncogenesis." (PMID 36394128, 2022). "Both HRAS and KRAS are frequently overexpressed in other cancer types as well." (PMID 36559011, 2022). "Unlike KRAS and NRAS, HRAS can only be prenylated by FTase; therefore, FTIs can still be useful for the treatment of HRAS-mutant cancers." (PMID 34200676, 2021). "TRPML1 knockdown or inhibition selectively reduced the proliferation of cancer cells that express oncogenic but not wild-type HRAS." (PMID 33803964, 2021). "A related study established that stimulation of mTORC1 with amino acids increases oncogenic H-Ras- but decreases K-Ras-nanoclustering via a phosphatidic acid-dependent mechanism downstream of SREBP1, with attendant consequences for spheroid growth of HRAS and KRAS mutant cancer cells." (PMID 33544116, 2021). "On the other hand, the evaluation of genes involved in the RAS signaling pathway (including the NRAS, HRAS and KRAS genes), a pathway involved in several cancer types, did not reveal any variant in our cohort." (PMID 34284772, 2021). "Notably, BCL2L1, E2F1, HRAS, MAPK8, MITF, RELA, and SP1 were found in both mitophagy and cancer pathways." (PMID 34262589, 2021). "In 2020, the FDA granted an expanded access program for the ERK inhibitor ulixertinib (BVD-523) for the treatment of cancer patients with abnormal MAPK pathways, including but not limited to those involving KRAS, NRAS, HRAS, BRAF, MEK, and ERK mutations." (PMID 34607583, 2021). "Toward this, we created a new Drosophila cancer model in which downregulation of Rbf1 is combined with downregulation of Pten and overexpression of Ras (Drosophila Ras85D is a single high-scoring ortholog of human KRAS, HRAS, and NRAS)." (PMID 33591981, 2021). "The anti-cancer effect of THSWD might by achieved via the down-regulation of MAPK1, HRAS, GRB2, AKT1, and MAPK14." (PMID 34513708, 2021). "Previous studies involving the HRAS gene in designing epitope-based vaccines to target cancer have resulted in T-cell proliferation, but have failed to result in significant tumor size reduction." (PMID 35062725, 2021). "The KRAS degrader specifically reduced proliferation of cells with mutant KRAS expression in 2D-adherent and 3D spheroid assays but did not modify the proliferation of cancer cell lines with mutant NRAS or HRAS nor of the RASWT cells HCC827 and MRC5." (PMID 32591521, 2020). "Members of the RAS family, such as NRAS, KRAS and HRAS, all of which are of significant importance in cancer biology, are no exception." (PMID 32772213, 2020). "In recent years, new trials have been initiated that are designed to target the HRAS driven cancers, as H-RAS is not subject to alternate prenylation." (PMID 31941155, 2020).
cancer (continued). "Compared with HRAS, both KRAS4B and NRAS were enriched for the “Central carbon metabolism in cancer” pathway, which includes proteins from the PIK3/Akt and MAPK pathways, glucose transporters, metabolic enzymes and tyrosine kinase receptors, all being frequently activated in cancer." (PMID 33187149, 2020). "In addition, while the expression of the cell cycle progression inhibitor CDKN1A (p21) was decreased in cancer EVs-exposed cells, the expression of the oncogenes MYC and HRAS was increased." (PMID 31200749, 2019). "In human cancers, oncogenic mutations commonly occur in the RAS genes KRAS, NRAS, or HRAS, but there are no clinical RAS inhibitors." (PMID 30194290, 2018). "We found that according to the KEGG enrichment of the common DEGs deregulated upon SOX2OT inhibition; the pathways related to cancer (Kegg: 05200) is one of the most significant enriched pathway (p-value = 0.009285) with 6 genes (HIF1A, HRAS, CHUK, PIK3CA, CDK2, VHL)." (PMID 30202240, 2018). "Conversely, we identified germline alterations in TSC2 and HRAS in two of our patients, with no pathogenic or likely pathogenic germline variants in those genes identified in the PHTS component cancers within TCGA." (PMID 29684080, 2018). "In tissues where expression of oncogenic HRAS promotes tumor formation, senescence markers are found abundantly in premalignant lesions but are absent in carcinomas." (PMID 28467300, 2017). "We conclude that inhibition of the PI3K pathway is not relevant for survival and cell growth of HRAS mutant cancer cells." (PMID 26544513, 2015). "HRAS-mutated cancers are still potential therapeutic targets of FTIs such as tipifarnib despite the negative results of FTIs against NRAS- or KRAS-mutated cancers." (PMID 40243851, 2025). "KRAS4B, but not HRAS, is also the target of an experimental cancer stem cell drug salinomycin." (PMID 41248180, 2025). "Non-recurrent, cancer-specific mutations (n = 28 genes across 11 cancers) predominantly correlated with high telomerase activity, with notable exceptions including PPP2R1A in UCS, HRAS, and GTF2I in THYM and SMAD4 in PAAD." (PMID 41321994, 2025). "HRAS is a GTP-binding protein that plays an important role in many cellular networks that control a variety of signaling pathways, such as growth regulation, proliferation, survival, differentiation, adhesion, and cell survival, all of which lead to many types of cancers on their disruption." (PMID 36982429, 2023). "The cancer target PDB ID 1RY0 (AKR1C3) showed the highest interactions with the majority of the NCs, followed by 1HFQ (DHFR), 3ZGC (NFE2L2), 4AF3 (AURKB), 4K33 (FGFR3), 5P21 (HRAS), 2I0V (CSF1R), and 3ZIM (PIK3CA) protein targets and least interaction was found with the 1M9Z (TGFBR2) protein." (PMID 36387366, 2022). "Additionally, we observed a negative correlation between MACC1 and two cancer and clock modulators, namely HRAS and SIRT1, known to affect the period of oscillation." (PMID 35884519, 2022). "The results indicate that CARM1 and CHK1 may not be a synthetic lethality to HRAS mutant-driven cancer cells." (PMID 35839996, 2022). "While WT RAS of the same isoform generally inhibits tumor initiation and growth, the protein products of the two non-mutated, WT RAS genes (for example HRAS and NRAS in a KRAS-mutated cancer; hereafter called WT RAS in all cases) are tumor promoting in RAS-mutated tumors." (PMID 33924994, 2021).